TTR (transthyretin)
Diseases named in the same sentence as TTR in open-access papers (continued):
Sharing a sentence is not in itself a finding about the gene and the disease.
amyloidosis (continued). "Transthyretin (TTR) is a globular protein whose misfolding and amyloid aggregation is related to amyloid transthyretin (ATTR) amyloidosis that consists of wild-type ATTR (ATTRwt) amyloidosis and variant ATTR (ATTRv) amyloidosis." (PMID 31861226, 2019). "This implies, however, that cellular conditions or genetic changes that favour multimers dissociation would also favour non-functional interactions, as it occurs in the case of human transthyretin or superoxide dismutase 1, whose dissociation leads to their aggregation and the onset of amyloidosis." (PMID 31398930, 2019). "Onset for familial TTR amyloidosis could occur within the second decade of life depending on the TTR mutant involved." (PMID 30934952, 2019). "We hope this study pave a road with stone leading to precision medicine of TTR amyloidosis." (PMID 31502419, 2019). "The first world-wide RNAi therapy has just been approved for TTR amyloidosis." (PMID 31440205, 2019). "For a multifactorial disease with a complex pathology such as TTR amyloidosis, plant extracts or products could provide potential multi-target therapeutic agents." (PMID 30934952, 2019). "The approval of patisiran (OnpattroTM) for the treatment of hereditary transthyretin-mediated amyloidosis in adults could probably be considered the most impressive breakthrough of recent years in the drug discovery arena." (PMID 30813407, 2019). "The first marketed RNAi therapeutic, approved in 2018, is Patisiran (Onpattro, Alnylam), administered for the rare misfolding disorder hereditary transthyretin (TTR) amyloidosis, where liver-derived amyloidic mutant TTR protein leads to multi-organ dysfunction." (PMID 33523197, 2019). "However, in TTR amyloidosis either due to single amino acid substitutions of TTR monomers or denaturation conditions, TTR tetramer disassembles into monomers following partial unfolding, and mis-assembles into amyloid fibril." (PMID 30704121, 2019). "Currently, there is no cure for TTR amyloidosis and treatment options are rare." (PMID 31835306, 2019). "Based on the mechanistic studies presented herein, we determined that CAB might be a potential candidate or source material for future therapeutic development for TTR amyloidosis and/or related neurodegenerative diseases." (PMID 30934952, 2019). "However, in 81 patients with TTR amyloidosis, an M protein was found in 20 of the 81 and an abnormal free light chain ratio in 8 of the 8124." (PMID 29795248, 2018). "In this study, we describe a Caenorhabditis elegans model that expresses various TTR fragments to elucidate the pathogenesis of C-terminal fragments of TTR in vivo, and we established this model as a tool for screening drug candidates for TTR amyloidosis." (PMID 30552363, 2018). "In TTR-related amyloidosis a phase-3 clinical trial is in the stage of patients recruitment." (PMID 30205618, 2018). "Assess the aqueous humor flare in transthyretin V30M amyloidosis patients (ATTRV30M)." (PMID 30327725, 2018). "Furthermore, a specific TTR antisense oligonucleotide (IONIS-TTR) was evaluated in an open label study examining functional and structural cardiac parameters in patients with either hereditary or wild type TTR amyloidosis." (PMID 30090066, 2018). "Therefore, many strategies to TTR amyloidosis prevention exploit its ability to bind small molecules in the T4 binding channel, mimicking its hormone binding capability, thereby producing kinetic stabilization of the tetramer." (PMID 29967786, 2018). "After siRNAs encapsulated in lipid nanoparticles were shown to successfully induce transthyretin knockdown in patients with TTR amyloidosis in a phase 1 study, a subsequent phase 2 study evaluated patisiran as a potential therapeutic strategy in TTR mediated familial amyloidotic polyneuropathy." (PMID 30090066, 2018).
amyloidosis (continued). "ECVCT also tracked various important clinical parameters including reduced 6-min walk test distance and increasing NT-proBNP, as well as amyloid burden in transthyretin-related amyloid—when measured semi-quantitatively by 99mTc-3,3-diphsphono-1,2-propanodicarboxylic acid (DPD) scintigraphy." (PMID 29511861, 2018). "Furthermore, additional treatments against TTR amyloidosis have been experimented, among which there are gene therapy and the resorption of amyloid deposits." (PMID 29967786, 2018). "Measurement of the thickness of the interventricular septum may suggest the typeof amyloidosis present in the patient, and is often greater in cases ofamyloidosis by TTR than the AL form, and may in many cases be greater than 20mm." (PMID 28678923, 2017). "Hereditary ATTRV30M amyloidosis is a lethal autosomal dominant sensorimotor and autonomic neuropathy due to the deposition of amyloid fibrils, in which the main polypeptide is aberrant transthyretin (TTR)." (PMID 28407005, 2017). "Besides, several compounds have been proposed as drugs in the therapy of TTR amyloidosis due to their TTR tetramer binding affinities, and therefore, contribution to its integrity." (PMID 28704493, 2017). "Hereditary ATTR (hATTR) amyloidosis, formerly known as familial amyloid polyneuropathy (FAP), is a progressive, life-threatening disease caused by misfolded transthyretin (TTR) protein that accumulates as amyloid fibrils in multiple organs, including the nerves, heart, and gastrointestinal tract." (PMID 28893208, 2017). "Data concerning the effects of the complement on TTR amyloidosis however is scarce." (PMID 28407005, 2017). "It is of considerable interest that the destabilization and loss of the native state of normally tetrameric transthyretin has been found to promote subsequent aggregation of transthyretin into the β-sheet rich pathologic amyloid found in patients with transthyretin amyloidosis." (PMID 28287086, 2017). "Among them, transthyretin(TTR) results as a possible molecular target of amyloidosis disruption." (PMID 28704493, 2017). "Collectively, these data support the hypothesis that TTR reduction has the potential to stabilize the progression of – or even reverse – neuropathy in patients with hATTR amyloidosis." (PMID 28893208, 2017). "The most common forms of amyloidosis are amyloid light-chain (AL or primary systemic), as was the case for our patient; amyloid A (AA or secondary systemic); and familial (abnormal amyloid transthyretin [ATTR])." (PMID 27026530, 2016). "Native state stabilizers are promising drugs to treat TTR amyloidoses." (PMID 26902880, 2016). "Misfolding of transthyretin (TTR), a human serum transport protein, is the root cause of a group of amyloidoses for which no FDA approved treatment currently exists." (PMID 27122057, 2016). "Therefore, additional alternative, potent and safe small molecules are still needed to effectively treat the TTR amyloidoses." (PMID 26902880, 2016). "We hypothesized that tissue-resident macrophages in familial amyloid polyneuropathy (FAP) patients will exhibit qualitative or quantitative abnormalities, that may accelerate transthyretin (TTR)-derived amyloid deposition." (PMID 27695122, 2016). "Transthyretin-derived (ATTR-) amyloidosis occurs as hereditary form due to a point mutation in the TTR gene or as wildtype variant without a germline mutation." (PMID 26915034, 2016). "The flavonoids represent an interesting group of drug candidates for TTR amyloidosis." (PMID 26020516, 2015). "Only the non-pathogenic T119M TTR variant, expression of which actually protects carriers of amyloidogenic mutations from developing amyloidosis, is resistant to proteolysis and fibrillogenesis." (PMID 26286619, 2015). "Amyloid cardiomyopathy is frequently encountered in patients with transthyretin (ATTR) amyloidosis." (PMID 26600306, 2015).
amyloidosis (continued). "Our findings may implicate neuronal toxicity subjacent to subpial and subependymal TTR amyloid deposits in the pathogenesis of the dementia and ataxia." (PMID 26156087, 2015). "Furthermore, clinical features of TTR-related amyloidosis include seizures and stroke-like episodes, reminiscent of our observations of seizure-like episodes that are associated with Foxl2−/− postnatal death." (PMID 26134413, 2015). "Contrarily to other TTR amyloidoses, L12P cases present liver TTR deposition." (PMID 25519307, 2014). "However, little is known about the efficacy of tafamidis in non-V30M FAP as well as in other TTR-related amyloidoses, involving cardiac and neurological manifestations." (PMID 25086037, 2014). "A remarkable achievement was done in 2008, when SNALP-based systems formulated two different RNAi payloads against VEGF and kinesin spindle protein (KSP) in a single vehicle and systemically given to patients with liver cancer and transthyretin (TTR)-mediated amyloidosis (ATTR)." (PMID 26056574, 2014). "In addition to full-length WT TTR, truncated C-terminal WT TTR fragments starting at positions 46–52 are usually detected in amyloid deposits obtained from SSA patients." (PMID 25228988, 2014). "We are confident that these findings will be helpful for a better understanding of the properties and dynamics of wild-type transthyretin, and may lead to exploitable information to counter amyloidosis." (PMID 25485123, 2014). "It is important to remember that amyloids are also the signature of systemic amyloidoses, a group of fatal diseases in which organs other than the CNS accumulate ordered aggregates of proteins, including transthyretin, immunoglobulin light chains and islet amyloid polypeptide." (PMID 25437612, 2014). "TTR amyloidosis is a progressive and fatal disease that is increasingly diagnosed worldwide." (PMID 23425518, 2013). "In recent years, many studies have been performed on TTR to address its involvement in several amyloid diseases such as senile systemic amyloidosis (SSA), familial amyloid polyneuropathy (FAP), familial amyloid cardiomyopathy (FAC) and central nervous system amyloidosis (CNSA)." (PMID 24358189, 2013). "TTR amyloidosis also encompasses an age-related amyloidosis known as senile systemic amyloidosis, an acquired disorder mainly affecting men after the age of 60 years, that results from the deposition of wild-type TTR amyloid." (PMID 23425518, 2013). "Additionally, Alnylam Pharmaceuticals is currently developing two SNALP encapsulated siRNA drugs that targeted the transthyretin (TTR) gene to treat TTR-mediated amyloidosis (ATTR)." (PMID 23667320, 2013). "In the case of islet-derived TTR, it has been theorized that the protein could affect the processing of glucagon, and furthermore that it may influence deposition of islet amyloid, which is found in at least 95% of subjects with Type II diabetes mellitus." (PMID 23840311, 2013). "The dual effect of EGCG both as TTR aggregation inhibitor and amyloid fibril disruptor together with the high tolerability and low toxicity of EGCG in humans, point towards the potential use of this compound, or optimized derivatives, in the treatment of TTR-related amyloidoses." (PMID 22253829, 2012). "However, since serum amyloid P component (SAP) is a universal marker of amyloid its reduction points towards a direct effect of EGCG on TTR amyloid removal." (PMID 22253829, 2012). "Hence, less aggressive therapies for the treatment of TTR amyloidosis such as stabilization of the soluble circulating amyloid precursor, inhibition of aggregation of amyloidogenic intermediates and disruption of insoluble deposits have been proposed." (PMID 22253829, 2012). "First, native TTR also forms amyloid in systemic senile amyloidosis, a geriatric disease." (PMID 22053176, 2011).
amyloidosis (continued). "Studies have shown that oxidative stress is increased in patients with amyloidosis, and in vitro studies have demonstrated that oxidative stress inhibits the initial rate and extent of amyloid fibril formation of wild-type as well as V30M transthyretin." (PMID 20840742, 2010). "The new TTR fibrillogenesis inhibitors are based on the diflunisal core structure because diflunisal is a registered salicylate drug with NSAID activity now undergoing clinical trials for TTR amyloid diseases." (PMID 19125186, 2009). "Against thisbackground, we questioned whether IAPP-amyloid could induce TTR-fibrilformation, and also whether deposition of TTR-amyloid in the pancreas leads toislet amyloidosis, either by deposition of fibrils from TTR or from IAPP." (PMID 18825272, 2008). "Transthyretin (TTR) is a major amyloid fibril protein in certain systemic forms of amyloidosis." (PMID 18825272, 2008). "However, other types, such as senile with normal transthyretin (ATTR), amyloidosis associated with Alzheimer's disease (Aβ), and islet amyloid polypeptide deposits (AIAPP) are very strongly associated with both old age and the aging process." (PMID 16138931, 2005). "However, mutations in the encoding TTR gene on chromosome 18q12.1 can lead to misfolding and cellular aggregation of the TTR protein, resulting in various clinical tissue manifestations of amyloidosis, mainly as cardiomyopathy form (HCM), kidney insufficiency and neuropathy." (PMID 39963604, 2025). "In addition, the peptides do not bind to amorphous aggregates formed at acidic pH and physiological temperature in vitro, in contrast to the previously reported findings that these peptides recognize ex vivo TTR fibrils derived from patients with TTR amyloidosis." (PMID 40816471, 2025). "Notably, Tg-induced ERS promoted the secretion of TTR in non-native tetrameric conformations, and these aggregates are typically closely associated with distal toxicity in the pathogenesis of TTR amyloidosis." (PMID 40666113, 2025). "Therefore, this ASO is advised only for TTR amyloidosis patients with a daily proteinuria <1 g/day." (PMID 40755967, 2025). "Thus, routine evaluation of sTTR levels may serve as a potential and informative biomarker of drug efficacy and treatment response at an individual level, reflecting TTR stability and a decrease in new amyloid formation in patients with amyloidosis." (PMID 40717228, 2025). "Approximately 9% of known TTR mutations do not cause amyloidosis." (PMID 39092395, 2024). "Cardiac amyloidoses are grouped under three headings: AL amyloidosis due to amyloidogenic monoclonal light chain production of a plasma cell clone; hereditary TTR amyloidosis (ATTRv) caused by accumulation of mutated Transthyretin (TTR); and wild-type (non-hereditary) TTR amyloidosis (ATTRwt)." (PMID 38111336, 2024). "Also, when abdominal fat pad biopsy is negative, the diagnostic yield of rectal biopsy is so low that it is no longer suggested as an alternative site, while sural nerve biopsy gives promising results by detecting 80% of TTR amyloidosis particularly in patients with familial amyloid polyneuropathy." (PMID 38333414, 2024). "Further, TTR is a serum transporter for thyroid hormones and retinol binding proteins that has been shown to be detrimental when misfolded and aggregated in various forms of amyloidosis, while also having evidence of protective effects in Alzheimer’s disease (AD)." (PMID 38990919, 2024). "Importantly, wild-type TTR is also responsible for a relatively common, aging-related, nonhereditary type of amyloidosis termed senile systemic amyloidosis or wild-type TTR amyloidosis (ATTRwt amyloidosis), where the heart is the main affected organ." (PMID 38907862, 2024).
amyloidosis (continued). "Two types of amyloid account for 95% of cardiac amyloidosis: light-chain amyloid (AL) due to immunoglobin light-chain deposition and transthyretin (TTR) cardiac amyloidosis (ATTR-CM), which can be due to hereditary mutation (hATTR) or wild-type transthyretin (wtATTR)." (PMID 38359001, 2024). "Notably, the cysteine 10 of TTR has previously been assigned a critical role in vivo and by replacing it with a serine, amyloid formation was prevented in a transgenic mouse model for TTR amyloidosis." (PMID 39615680, 2024). "However, a common inherited pathological TTR variant exists in more than 1.5 million people in the US, but the proportion of variant carriers who develop clinical manifestations of amyloidosis is not well defined." (PMID 39540049, 2024). "The combination of biomechanical forces and proteolytic activity, which occurs in cardiac TTR amyloidogenesis, fits with the concept of a mechano‐enzymatic mechanism as a pathological process, which is also well described for a relevant physiological process unrelated to amyloid diseases." (PMID 38380705, 2024). "Other PTMs include oxidative modification of Met and Cys residues, together with protein carbonylation, which imparts cytotoxicity to TTR toward human cardiomyocyte cell, indicating that the oxidative modifications of TTR due to aging may contribute to ATTRwt amyloidosis." (PMID 38233673, 2024). "Of these, 96 were excluded because they lived outside the state of Rio de Janeiro, 79 refused to participate, 25 could not be contacted by phone, 9 were participating in a double-blind study at the time of evaluation, 8 had an eGFR < 45 mL/min/1.73m2, 5 had non-TTR amyloidosis, and 1 was pregnant." (PMID 39101566, 2024). "In another study comparing 96 patients with cardiac amyloidosis (AL, wild-type TTR, and mutant TTR amyloidosis) and 91 patients with non-amyloid causes of cardiac hypertrophy, hs-TnT levels were significantly higher in the cardiac amyloidosis group than in the other hypertrophy group." (PMID 38472975, 2024). "We also determined whether non-carriers of TTR V142I with heart failure or arrhythmia plus other non-cardiac manifestations of amyloidosis had other TTR variants." (PMID 38541013, 2024). "In addition, Onpattro®, a recently approved liposomal therapy for the treatment of transthyretin-mediated (ATTR) amyloidosis, is a double-stranded siRNA formulated into lipid nanoparticles targeted to primary synthetic Hepatocytes at the site of TTR to inhibit the synthesis of TTR." (PMID 37009262, 2023). "However, currently, HT alone may be an option as TTR-specific therapy, such as tafamidis or a silencing agent (in patients with ATTRv-CM), can be prescribed post-transplant if coexisting amyloidosis-related polyneuropathy is present." (PMID 37901600, 2023). "Additionally, PET imaging, which can mark TTR amyloidosis, can help address this issue." (PMID 36198883, 2023). "In addition to established co-morbidities, a clustering of transthyretin (TTR) amyloidosis in LFLG patients (up to 30% prevalence) can now be reasonably assumed, which may further explain the adverse outcomes observed in comparison with HG AS patients." (PMID 38028449, 2023). "ATTR amyloidosis may be caused by one of over 130 pathogenic mutations that destabilize the TTR protein (hereditary ATTR amyloidosis [ATTRv amyloidosis]) or the accumulation of non-mutated TTR protein (wild-type ATTR amyloidosis [ATTRwt amyloidosis])." (PMID 37946256, 2023). "TTR misfolding can originate either from inherited mutations in the TTR gene, which results in the variant form of the disease (ATTRv), or it can develop spontaneously due to the incorrect folding of the non-mutated TTR, leading to the so-called wild-type ATTR (ATTRwt) amyloidosis." (PMID 37784196, 2023). "In ATTRwt amyloidosis, wild-type, non-variant TTR dissociates, and amyloid aggregation occurs." (PMID 37740174, 2023). "Finally, TTR is the pathogenetic agent of a form of amyloidosis." (PMID 35386059, 2022).